G6PD (glucose-6-phosphate dehydrogenase)
Diseases named in the same sentence as G6PD in open-access papers (continued):
Sharing a sentence is not in itself a finding about the gene and the disease.
vivax malaria (continued). "All respondent agreed that G6PD testing was not undertaken in patients with vivax malaria prior to prescribing PQ; however many mentioned that access to G6PD testing was desirable.“Yes it would be [useful]." (PMID 28797255, 2017). "PQ should not be administered to patients with vivax malaria without previous evaluation of their G6PD status." (PMID 26753754, 2016). "Concern regarding potential harm at the higher dose without G6PD screening explains that recommendation (see section Chemotherapeutic policy for vivax malaria)." (PMID 27708185, 2016). "In the past, some countries aiming for vivax malaria eradication deployed mass treatments with primaquine on a massive scale, without G6PD testing." (PMID 24502194, 2014). "In the case of vivax malaria, a lack of diversity in the overall decision-making process may also result in less focus on addressing the needs of specific populations such as G6PD heterozygous females." (PMID 34717642, 2021). "However, in many endemic areas of vivax malaria, patients are treated with PQ without any evaluation of their G6PD status." (PMID 26753754, 2016).
breast cancer (92 papers, 1971 to 2026). A primary or metastatic malignant neoplasm involving the breast. "Of special note, TCGA database analysis of the association between G6PD level and breast cancer prognosis demonstrated that high G6PD expression level was closely correlated with poor prognosis of breast cancer, which is also verified in a variety of tumors." (PMID 38110365, 2023). "Increased expression of G6PD is a predictive indicator of high risk of relapse and metastasis in patients with breast cancer." (PMID 35806424, 2022). "G6PD, one of the PPP-related enzymes, is associated with the molecular subtype of breast cancer, and G6PD overexpression is associated with poor prognosis of breast cancer." (PMID 34552932, 2021). "In this manuscript, we describe for the first time that the inhibition of G6PD causes an activation of autophagic flux, which synergistically increases the cytotoxic effect of Lapatinib on breast cancer cells." (PMID 30987650, 2019). "We finally provided strong evidence to support the fact that high expression of TKT and G6PD is associated with poor outcome in breast cancer patients." (PMID 29290982, 2017). "Further, by using gene expression data sets and tissue microarray from breast cancer patients, we showed that G6PD was associated with outcomes in patients with breast cancer." (PMID 27078845, 2016). "In conclusion, this study did demonstrate that the overexpression of G6PD in primary breast carcinomas was associated with a high risk of recurrent metastasis and poor PFS." (PMID 26607846, 2015). "In breast cancer, 17 genes were associated with poor prognosis, such as glucose-6-phosphate dehydrogenase (G6PD), heme oxygenase (decycling) 1 (HMOX1) and thioredoxin reductase 1 (TXNRD1), and only 2 with good outcome." (PMID 24342878, 2013). "G6PD was significantly associated with breast cancer grade lymph node metastasis (p = 0.021)." (PMID 35154262, 2021). "Furthermore, high expression levels of G6PD are associated with a decreased overall relapse-free survival of breast cancer patients." (PMID 31488102, 2019). "Importantly, we showed using breast cancer patient datasets that expression of both enzymes is positively correlated and that high expression levels of G6PD and TKT are associated with decreased overall and relapse-free survival." (PMID 29290982, 2017). "The G6PD protein could be served as a potential prognostic biomarker for primary breast carcinoma, and overexpression of G6PD protein predicted a high risk of recurrent metastasis and poor PFS during follow-up." (PMID 26607846, 2015). "Gene-disease associations further prioritized G6PD, SLC2A1, and TK1 as robust targets strongly linked to lung and breast cancers." (PMID 42241400, 2026). "G6PD is overexpressed in different cancers, including gastric cancer 35, bladder cancer 36, and breast cancer." (PMID 40303290, 2025). "They identified cross-reactivity between anti-Setaria equina antibodies and cell extracts from Huh-7 hepatoma and MCF-7 human breast cancer cells at 75 and 70 kDa, potentially corresponding to Glucose-6-phosphate dehydrogenase and HSP-70, respectively." (PMID 40402283, 2025). "Inhibition of one of these NADPH-generating enzymes, glucose-6-phosphate dehydrogenase, has been demonstrated in breast cancer in both 2D cellular models as well as a nude mouse model to have an excellent inhibitory proliferative effect." (PMID 40839139, 2025). "For instance, higher expressions of 6-phosphogluconolactonase (6PGL) and glucose-6-phosphate dehydrogenase (G6PD) suggest that the HER2 subtype of breast cancer has a more active PPP than other subtypes." (PMID 39791706, 2024). "6‐aminonicotinamide (6‐AN), an analogue of NADP that directly antagonizes G6PD activity, significantly decreased viability, colony formation capacity, and migration of breast cancer cells, leading to ROS upregulation and abnormal autophagy." (PMID 38115544, 2024).
breast cancer (continued). "Nuclear receptor binding SET domain protein 2 (NSD2), which is upregulated in breast cancer, elevates the expression of G6PD to promote the proliferation of breast cancer cells." (PMID 39516455, 2024). "With these findings in mind, we hereby confirmed the crucial role of G6PD level in breast cancer prognosis, which inspired us to probe the potential impact of G6PD in the combination therapy of pyrotinib plus chrysin against HER2-positive breast cancer." (PMID 38110365, 2023). "Meanwhile, the PYGL and G6PD levels in the primary tumors, including breast cancer, lung adenocarcinoma, and colon cancer, were positively correlated with poor patient survival." (PMID 38099490, 2023). "Knocking down p52-ZER6 clearly suppressed the expression of G6PD in breast cancer and hepatocellular cancer cells, while its overexpression had the opposite effect, suggesting that such regulatory action was common to various cancer types." (PMID 36977688, 2023). "To establish a correlation between G6PD enzymatic activity and phosphorylation level, we ectopically expressed HA-SRC along with Flag-G6PD in breast cancer cells." (PMID 37491277, 2023). "In agreement with observations, it is clearly demonstrated that the combination treatment of pyrotinib and chrysin synergistically potentiates autophagy in HER2-positive breast cancer cells via regulating miR-16-5p/ZBTB16/G6PD axis." (PMID 38110365, 2023). "Studies have manifested that G6PD expression is increased in melanoma, breast cancer, lung cancer, liver cancer, and colorectal cancer, and G6PD plays an important role in the occurrence and development of tumors." (PMID 38180104, 2023). "Increased G6PD activity has been reported in breast cancer cells upon 17 β-estradiol administrations." (PMID 36992836, 2023). "RIP140 inhibits the expression of G6PD in breast cancer cells and in immortalized or transformed mouse embryonic fibroblasts (MEFs) from RIP140 knock-out (RIPKO) mice." (PMID 35806424, 2022). "In breast cancer cells, it was shown that the overexpression of Nrf2 augments the expression of Notch1 via G6PD/HIF-1α pathway." (PMID 35417854, 2022). "Elevated NRF2 enhanced the growth and motility of breast cancer cells by upregulating a pivotal enzyme of the pentose phosphate pathway, i.e., the glucose-6-phosphate dehydrogenase (G6PD)." (PMID 36185256, 2022). "Altogether, this study describes a novel role for RIP140 in regulating G6PD levels, which links its effect on breast cancer cell proliferation to metabolic rewiring." (PMID 35806424, 2022). "We next conducted both time-course and dose-response studies for the effects of R001 on both G6PD and TrxR1 functions in the breast cancer cells." (PMID 36473850, 2022). "Here, we show that, in human breast cancer cells and mouse embryonic fibroblasts, RIP140 inhibits the expression of the gene-encoding G6PD, the first enzyme of the PPP." (PMID 35806424, 2022). "Analysing PPP gene mRNA level using RT-qPCR revealed that G6PD was the only PPP gene deregulated after RIP140 down-regulation in both breast cancer cells." (PMID 35806424, 2022). "Here, we identify RIP140 as a novel transcriptional regulator of G6PD expression in breast cancer cells." (PMID 35806424, 2022). "Altogether, our data reveal a new regulator of the oxidative branch of the PPP through the inhibition of G6PD expression and, consequently, breast cancer cell proliferation." (PMID 35806424, 2022). "G6PD acts as an oncogene in many types of cancers and Nrf2 promotes breast cancer cell migration via up-regulation of G6PD/HIF-1α/Notch1 axis." (PMID 35818395, 2022). "For TNBC, CD44, FDFT1, G6PD, and GLS2 were significantly associated with breast cancer grade (all p < 0.05)." (PMID 35154262, 2021). "Among the numerous metabolic pathway-associated genes, the high expression of GLUT1, G6PD, TKTL1 and PGI/AMF are significantly correlated with decreased survival in breast cancer." (PMID 33723286, 2021).
breast cancer (continued). "G6PD activity is increased in several types of cancers, including bladder cancer, breast cancer, prostate cancer and ovarian cancer." (PMID 34423480, 2021). "The blockade of G6PD by autophagy enhanced the inhibitory effect of tyrosine kinase on breast cancer cells." (PMID 34059009, 2021). "This led us to investigate the effect of G6PD blockade on autophagy and its role in breast cancer cells response to treatment." (PMID 30987650, 2019). "Further study on Nrf2/G6PD/HIF‐1α/Notch1 signalling axis is demanded for realization of basal type breast cancer treatment." (PMID 30809937, 2019). "In summary, our findings suggest that Nrf2 contributes to metastatic ability of basal type breast cancer cells through G6PD/HIF‐1α/Notch1 signalling axis." (PMID 30809937, 2019). "G6PD is suggested to be essential for cell survival and inhibition of G6PD reduces proliferation and cell survival in breast cancer cells." (PMID 31488102, 2019). "In this study, we investigated the interplay between G6PD, ER stress and autophagy, and highlighted new possible strategies to improve the effect of TKIs in treatment of breast cancer overcoming drug resistance." (PMID 30987650, 2019). "Treatment of breast cancer cell lines with l-arginine in combination with 5-FU enhances apoptosis and decreases metastases by targeting G6PD." (PMID 31500396, 2019). "In order to detect the effect of Nrf2 on PPP in breast cancer, expression of G6PD and TKT was detected by RT‐PCR and western blotting in MCF‐7 and MDA‐MB‐231 cells." (PMID 30809937, 2019). "Inhibiting G6PD in breast cancer cells synergistically enhances the anti-HER2 tyrosine kinase inhibitor-induced cytotoxic effect." (PMID 31500396, 2019). "Particularly, we selected MCF7 cells because they reportedly show increased expression of G6PD compared with the near-normal breast cancer cell line MCF10." (PMID 29290982, 2017). "We also assessed the efficiency of mammosphere formation, another surrogate marker for CSC self-renewal, by treating breast cancer cell lines with inhibitors of G6PD and PPP." (PMID 27078845, 2016). "We found a trend toward worse disease-specific survival among breast cancer patients with high G6PD protein levels (p = 0.06), mirroring the outcomes for patients with high G6PD mRNA expression." (PMID 27078845, 2016). "Further studies were certainly needed for this issue on a large number of patients with primary breast carcinomas and to clarify the role of G6PD protein or other else in breast cancer progression." (PMID 26607846, 2015). "We evaluated the effects of DHEA on G6PD activity and on the in vitro proliferation of two human breast cancer cell lines, MCF-7 (steroid receptor positive) and MDA-MB-231 (steroid receptor negative), in a serum-free assay." (PMID 9052415, 1997). "Arginase and glucose-6-phosphate dehydrogenase activities in the mammary glands of 4, 8 and 12 month old groups and in precancerous nodules and mammary tumours in (C3H Jax) virgin mice were studied." (PMID 5581293, 1971). "The inhibition of G6PD by polydatin, a glucoside of resveratrol used for many years to treat different pathological conditions, induces endoplasmic reticulum stress and autophagy in breast cancer cells." (PMID 38115544, 2024). "G6PD inhibition can also promote endoplasmic reticulum stress and the perturbation of autophagic flux, thus synergistically increasing the effect of lapatinib on breast cancer cells." (PMID 39061847, 2024). "Thus, G6PD inhibition directly enhances the lapatinib cytotoxic effect on breast cancer cells, while autophagy blocking reverses this effect." (PMID 39539439, 2024).
breast cancer (continued). "Additionally, in CTCs from breast cancer patients, upregulation of glucose-6-phosphate dehydrogenase (G6PD), a key enzyme in the pentose phosphate pathway (PPP), has been correlated with tumor metastasis and progression." (PMID 38898058, 2024). "Inhibition of G6PD in mouse models also led to reduced tumor growth, suggesting that targeting G6PD may be a novel strategy for systemic breast cancer therapy." (PMID 39796677, 2024). "Besides, TCGA database analysis revealed that high G6PD expression level was closely correlated with poor prognosis of breast cancer, which is also verified in a variety of tumors." (PMID 38110365, 2023). "Conversely, it has been shown that glucose-6-phosphate dehydrogenase was increased in breast cancer cells that were undergoing ferroptosis induced by erastin, and this may be seen as a compensatory mechanism." (PMID 36837761, 2023). "The consequences of G6PD inhibition, including inhibited cell proliferation, increased oxidative stress, and enhanced glycolytic pathway, were reported in the breast cancer cell line MCF7 and are consistent with our observations reported here and before, i.e., decreased proliferation." (PMID 38001783, 2023). "In summary, our study identifies for the first time the tremendous therapeutic potential of pyrotinib combined with chrysin in treating HER2-positive breast cancer but also sheds light on the functional role of miR-16-5p/ZBTB16/G6PD axis in the anti-HER2 therapeutic process." (PMID 38110365, 2023). "We found that the combination treatment of pyrotinib and chrysin dampened the G6PD expression in HER2-positive breast cancer cells, whereas overexpression of miR-16-5p or knockdown of ZBTB16 increased the G6PD expression in breast cancer cells, along with apparently decreased autophagy." (PMID 38110365, 2023). "We could repeat this result by down-regulating RIP140 and G6PD expression concomitantly by siRNA in the breast cancer cell lines MDA-MB-436 and MCF7." (PMID 35806424, 2022). "Our results suggest that targeting G6PD with inhibitors in breast cancer patients that have a low level of RIP140 expression might be more efficient." (PMID 35806424, 2022). "Moreover, G6PD inhibition by a specific inhibitor resulted in a reduction in the growth of RIP140-KO MEF tumors and of RIP140-deficient breast cancer cells." (PMID 35806424, 2022). "Estradiol is also known to regulate G6PD expression and activity in breast cancer." (PMID 35806424, 2022). "Since in our previous studies, we observed increased glutamine consumption in breast cancer cells with reduced G6PD activity, we aimed to investigate whether G6PD expression is modulated by glutamine deprivation." (PMID 34572981, 2021). "In the previous studies performed within our team using breast cancer cell lines, we demonstrated that the inhibition of glucose 6-phosphate dehydrogenase (G6PD), the first enzyme of ox-PPP, leads to a decrease in cell proliferation and alterations in the central carbon metabolism." (PMID 34572981, 2021). "In a recent study, it was demonstrated that the overexpression of NRF2 can promote the proliferation and migration of breast cancer cells by upregulating the expression of glucose-6-phosphate dehydrogenase (G6PD), a key enzyme in the pentose phosphate pathway (PPP)." (PMID 33805996, 2021). "Therefore, the authors concluded that NRF2 plays an essential function in the regulation of breast cancer malignancy by influencing the Notch1 signaling pathway through the upregulation of G6PD, a rate-limiting enzyme of the PPP." (PMID 33805996, 2021). "However, G6PD silencing did moderately decrease lung colonisation when breast cancer cells were delivered through tail-vain injection." (PMID 34932167, 2021).